GPNMB (glycoprotein nmb)
Diseases named in the same sentence as GPNMB in open-access papers (continued):
Sharing a sentence is not in itself a finding about the gene and the disease.
tumor (continued). "Accumulated evidence revealed that LAMs shared a high expression of typical genes (such as APOE, APOC1, GPNMB, TREM2, SPP1 etc.)and played a central role in tumor immunity." (PMID 38346944, 2024). "The results demonstrated that CX3CR1+, C1Q+, and GPNMB+ macrophages exhibited the highest interaction with NR5A1+, TBX19+, and POU1F1+ tumor cells, respectively." (PMID 38658971, 2024). "Immunosuppression heightens the likelihood and severity of HNC, with lactic acid-induced immunosuppression mediated by GPNMB and CD44 in the tumor microenvironment contributing to cancer progression." (PMID 39040446, 2024). "GPNMB+ TAM more often accumulated at the tumor margin, therefore more exposed to tumor immunosuppressive signals, favor tumor growth and metastasis." (PMID 38408082, 2024). "Among them, the TREM2+ subpopulation was characterized by high expression of GPNMB, TREM2, ACP5, LGMN, and TIMP2, and mainly distributed at the boundary and core region of the tumor." (PMID 38948071, 2024). "The expression of chemoresistance genes has been detected, including KLF4 (doxorubicin and ifosfamide), ULK1, LUM, GPNMB, and CAVIN1 (doxorubicin), and AHNAK2 (gemcitabine) in tumor cells and ETS1 (gemcitabine) in TME." (PMID 39685635, 2024). "For example, the tumour cell expressed genes CD24, CLU, and SLPI35–37 and the infiltrating cell expressed genes GPNMB, MGP, GPX3, and MFAP438–41 have all been previously associated with poor prognosis and chemotherapy resistance in HGSOC." (PMID 38570491, 2024). "Longitudinal immunoPET imaging of gpNMB expression is feasible, given that [89Zr]Zr-DFO-CR011 internalizes in the tumor cell rapidly after binding to gpNMB on the cell surface." (PMID 36900378, 2023). "Another approach is to increase gpNMB expression to efficiently deliver the MMAE payload and sensitize the tumor cells to ADC treatment." (PMID 36900378, 2023). "Therefore, GPNMB may serve as a novel tumour therapeutic target and prognostic marker of ESCC." (PMID 36090016, 2022). "The proposed mechanism of action is that upon the binding of GPNMB, the complex is internalized, MMAE is released in the lysosome, and tumor cell death occurs as a result of microtubule-inhibition mediated apoptosis." (PMID 32823698, 2020). "If they are, the process is consistent with the previously reported finding that GPNMB is cleaved by ADAM10 and secreted extracellularly in breast cancer cells." (PMID 32188902, 2020). "GPNMB and CoL5A1 are the reported oncogenes; PMEPA1, POMT2, VGLL4 and SUMF1 show better survival and thus suggest tumor suppressive role are being regulated by EZH2 signifying its dual role." (PMID 30760814, 2019). "GPNMB levels were also found to be higher in CSF from PCNSL patients than from control patients, and therefore likely originated from tumor cells as well." (PMID 29299134, 2017). "Quantification of tumor uptake at 4 and 7 days p.i. determined that [89Zr]DFO-CR011 had a mean SUV of 2.9 ± 0.6 in the gpNMB-positive xenograft versus 1.6 ± 0.5 in the gpNMB-negative model (P < 0.05) at 4 days p.i.." (PMID 29262642, 2017). "To assess the role of GPNMB/OA ECD in promoting in-vivo tumor growth, we developed tumor xenografts in athymic (nu/nu) mice using calu-6 cells (with low GPNMB/OA mRNA expression)." (PMID 26883195, 2016). "The investigators showed that GPNMB/OA ECD protein is cleaved and shed (primarily mediated by ADAM-10) from the tumor cell surface, producing ECD fragments." (PMID 26883195, 2016). "In order to investigate the in vivo localization of ADAM23, GPNMB and PRSS3, human tumor tissues were analyzed by in situ hybridization." (PMID 18447899, 2008). "Under both conditions the expression of ADAM23, FAP, GPNMB and PRSS3 genes was much higher in EC isolated from tumor specimens, as shown by the fold difference values." (PMID 18447899, 2008).
tumor (continued). "By IHC and immunoblotting, STP tumor cells showed strong expression of nuclear TFE3, the canonical TFE3 target GPNMB, as well as expression of melanocytic and lysosomal markers (PMEL, MelanA and Cathepsin K) commonly upregulated in human MiT/TFE-related neoplasms." (PMID 41044182, 2025). "Tumor endothelial cells (TECs) induce CD8+ TIL exhaustion via glycoprotein nonmetastatic melanoma protein B (GPNMB) expression." (PMID 40097979, 2025). "Next, we leveraged the Ivy-GBM cohort to integrate the transcriptional signatures of MES-like tumor cells, ICAM1+ MDMs, GPNMB+ MDMs, COL6A3+ TAFs, endothelial cells, and NK/T cells with distinct histological regions of GBM tissues, estimating the relative proportions of each cell cluster." (PMID 41174767, 2025). "Glycoprotein non-metastatic melanoma protein B (GPNMB), a transmembrane glycoprotein, has been recognized as a tumor promoter in different cancers." (PMID 40653468, 2025). "GPNMB affects the migration and infiltration of CD8+ T cells from tumor vessels into tumor tissues, leading to the functional exhaustion of CD8+ T cells, manifested as increased expression of inhibitory receptors, decreased IFN-γ production, and ROS accumulation." (PMID 41180454, 2025). "Glycoprotein Non-Metastatic Melanoma Protein B (GPNMB) is a transmembrane receptor that drives tumor progression by activating dual signaling pathways, namely Wnt/β-catenin and PI3K-AKT-mTOR." (PMID 41189944, 2025). "GPNMB binds to integrins such as α5β1/αvβ3 via the RGD motif in its extracellular domain, activating downstream MMP family members including MMP-2/9 to enhance tumor cells’ ability to degrade the extracellular matrix." (PMID 41180454, 2025). "The study has several limitations including the usage of a conventional knockout, providing only evidence of tumor growth impairment in murine models as well as not addressing interactions that upregulate GPNMB specifically in respective immune cells." (PMID 38566120, 2024). "Except for genes that might have been highly expressed in the lymph nodes (CCL21, LTB) and has already previously identified related to tumor metastasis gene (MMP9), we selected GPNMB as target gene for further study." (PMID 38706915, 2024). "Compared to GBM tissue, there was less and diffuse or even no detectable, expression of GPNMB in non-tumor samples." (PMID 38566120, 2024). "Additionally, we identify ligand signalling events occurring between tumour, stroma, and immune infiltrate regions, such as immune infiltrate derived GPNMB, which was highly correlated with VEGFA expression within the tumour." (PMID 38890455, 2024). "Expression of GPNMB was detected predominantly within the tumor margin (in the area with RFP+ cells), but not outside the tumor margin." (PMID 38566120, 2024). "Furthermore, we found a significant correlation between the total GPNMB+ and IBA1+ cells in non-tumor (r = 0.72; p = 0.0288) and GBM tissue (r = 0.85; p ≤ 0.0001)." (PMID 38566120, 2024). "MyD88 signaling pathway plays an essential role in GPNMB+MDSC‐mediated tumor immune escape during CAC development and is a promising focus for revealing the mechanisms of MDSC that facilitate immunosuppression and tumor progression." (PMID 38140790, 2023). "Since it was confirmed that the activity of EGFR can be enhanced by GPNMB, we further investigated whether CCN3-induced metastasis and tumor progression were mediated by GPNMB-induced mechanisms." (PMID 36737605, 2023). "ImmunoPET with [89Zr]Zr-DFO-CR011 could be used as an imaging tool to evaluate gpNMB upregulation with other strategies for combination treatment like that of HSP90 inhibitors and improve ADC delivery to tumor cells at the right time." (PMID 36900378, 2023). "Discordance between SUVmean in the tumor and tumor-to-heart SUVR, where SUVmean remained constant from 14 to 28 days post treatment initiation and tumor-to-heart SUVR decreased, indicates the possibility of shed gpNMB or increased bioavailability." (PMID 36900378, 2023).
tumor (continued). "It has been reported that tumor endothelial cells can induce tumor-infiltrating CD8 T cell exhaustion and promote the escape of cancer cells from immune surveillance by upregulating the expression of GPNMB." (PMID 36263422, 2022). "GPNMB triggers the self-renewal of spheroids to increase cell survival and the tumor-forming ability of macrophages interacting with tumor cells, and GPNMB activates the expression of the IL-33cytokine and its receptor, IL-1R1L, through CD47 and is sufficient to induce tumor spheroid formation." (PMID 35678671, 2022). "However, in mouse tumor models, M2 TAMs preferentially express soluble GPNMB and bind to the CD44 receptor on tumor cells to trigger CSC proliferation." (PMID 35740975, 2022). "In vitro study of GPNMB-expressing tumor cells showed no impact on cellular growth or death but increased expression of MMP-3 and MMP-9 as well as increased invasiveness." (PMID 34108545, 2021). "Though we had a high number of tumor tissue evaluated, the baseline and/or post-treatment tissue samples of some of the patients were not available for GPNMB expression." (PMID 32823698, 2020). "Moreover, enhancers of migration and angiogenesis such as GPNMB, PTGS2, CD274, and ZNF703 were significantly downregulated suggesting suppression of tumor malignancy." (PMID 31842391, 2019). "It was considered that since calu-6 cells produced the least amount of GPNMB/OA ECD protein, we expect that intratumoral injections of rOA could mimic the situation where GPNMB/OA ECD protein is shed into tumor tissues." (PMID 26883195, 2016). "In order to mimic the process of GPNMB/OA ECD protein shedding into tumor tissues, we developed an in-vivo tumor model in athymic (nu/nu) mice with or without exogenous supplementation of recombinant GPNMB/OA (rOA) that represents the ECD protein." (PMID 26883195, 2016). "We could demonstrate that combined GPNMB depletion and Tra treatment led induced a stronger effect on HER2-positive tumor suppression than Tra treatment alone." (PMID 26077887, 2015). "In contrast, three of four HER2-rich BC patients with low GPNMB (<5 ng/mL) showed faint or negative staining in tumor cells irrespective of a positive signal in stroma." (PMID 26077887, 2015). "Our own work here with patient serum exosomes implies that GPNMB and/or ERBB2 may be tumor-specific exosome markers." (PMID 22848702, 2012). "ADAM23 and GPNMB were expressed by a limited subset of tissues, while tumor cells did not express either one of them." (PMID 18447899, 2008). "We also measured expressions of FABP5, GPNMB and OLR1 in the tumors and adjacent tissues, and found that they were expressed at significantly higher levels in the tumors than in the adjacent normal tissues, again confirming the ability of spheroids to mimic the in vivo tumor." (PMID 40176808, 2025). "IBA1+ cells at a distance from the tumor were ramified and had no detectable GPNMB expression." (PMID 38566120, 2024). "Differential gene expression showed an enrichment of genes involved in T cell recruitment (CXCL9, CXLC10) and interferon-gamma activity (GBP1, STAT1) in the macrophage compartment of responding tumours, while non-responders were enriched in immunosuppressive markers (GPNMB, CCL18)." (PMID 38030622, 2023). "Another possibility could be tracer binding to shed gpNMB from tumor cells, but a limitation of our study is that we did not determine gpNMB concentration in the blood at the endpoint, and it should be explored further in future studies." (PMID 36900378, 2023). "It is noteworthy that little or no expression of GPNMB was detected in adjacent non-tumor tissues." (PMID 29552294, 2018). "RQ by RPL29 (T/N = 2.23×, p = 0.071), HPRT1 (T/N = 1.34×, p = 0.258), ACTB (T/N = 1.60×, p = 0.395), 18S rRNA (T/N = 1.36×, p = 0.527) and RPL29-HPRT1 (T/N = 1.76×, p = 0.086) also showed increasing GPNMB expression in tumor stomach tissues but it was not statistically significant." (PMID 20507635, 2010).
tumor (continued). "It is not clear whether the predominant tumor growth stimulatory effect of GPNMB/OA stems from impaired apoptosis or enhanced vascular recruitment; however, it is likely that the two processes are interrelated." (PMID 20711474, 2010). "However, selective targeting of gpNMB in the tumor versus in normal organs could not be assessed in the animal study, since the CR011 antibody binds selectively to human gpNMB." (PMID 33096754, 2020). "Glycoprotein NMB (GPNMB)-driven increases in NRP-1 expression in BC cells were reported to potentiate vascular endothelial growth factor (VEGF) signaling and tumor growth but not metastasis." (PMID 37175499, 2023). "The dasatinib and CDX-011 combination treatment significantly reduced the change in tumor volumes in MDA-MB-468 xenografted mice, while it did not have significant effects in the gpNMB-negative MDA-MB-231 models." (PMID 36900378, 2023). "Overall, 28 out of 43 patients (65%) whose tumours lacked a genomic match to a clinical trial were eligible for investigational drugs as a result of TMP analysis (PTEN, EGFR, HER2, GPNMB, MSLN, TROP2, TOPO1 or TOP2A as emerging positive predictive markers)." (PMID 31537838, 2019). "In PET studies at the optimal imaging timepoint of 7 days p.i., the [89Zr]DFO-CR011 tumor uptake in gpNMB-expressing MDA-MB-468 xenografts had a mean SUV of 2.9, while significantly lower in gpNMB-negative MDA-MB-231 tumors with a mean SUV of 1.9." (PMID 29262642, 2017).
cancer (99 papers, 2007 to 2026). A tumor composed of atypical neoplastic, often pleomorphic cells that invade other tissues. "Because of its functions in immune system activation, cell proliferation, angiogenesis, tissue repair, and the invasion and metastasis of malignant tumors, GPNMB has been implicated in various physiological and pathological processes." (PMID 37112900, 2023). "While overexpression of GPNMB is potentially another strategy for preventing the accumulation of senescent cells, it has a risk of promoting of cancer." (PMID 35444208, 2022). "It has been linked to promote cancer aggressiveness and implicated as a novel target for GPNMB-expressing cancers." (PMID 34108545, 2021). "Dysregulation of GPNMB expression has been identified to be associated with pathological progression, including aggressive cancers." (PMID 30484490, 2018). "We also observed a high induction of the glycoprotein, GPNMB (NM_053110.4), a melanosome-associated protein implicated in cancer metastasis." (PMID 21637858, 2011). "High levels of GPNMB expression have been associated with resistance to cancer therapies." (PMID 41174767, 2025). "GPNMB has been associated with various pathophysiological events, including cell adhesion, differentiation, senescence, inflammatory responses, neuronal degeneration, bone formation, T-cell activation, and metastasis in several cancers." (PMID 39947468, 2025). "We also identified alterations in genes involved in various critical biological processes: MDC1, associated with DNA damage response and drug resistance in MM; DAXX, involved in chromatin regulation; GPNMB, linked to immunosuppression in cancer; and XK, which plays a role in hematopoiesis." (PMID 39769182, 2024). "GPNMB has been implicated in the promotion of cancer cell metastasis through multiple mechanisms." (PMID 38706915, 2024). "However, it is important to notice that GPNMB is associated with cancer progression and metastasis." (PMID 34054862, 2021). "Crucially, GPNMB marks cancer stem cells in breast tumors, inducing EMT transcription factors and sphere-forming capacity without proliferation marker expression, suggesting a dormancy-associated stemness program." (PMID 41180454, 2025). "Pan-cancer studies have also shown that the ability of GPNMB to activate the PI3K-AKT pathway is positively correlated with the metastatic potential of tumors, and inhibition of its expression significantly reduces the invasiveness of DLBCL cells." (PMID 41189944, 2025). "GPNMB is markedly upregulated in cancer cells or the TME, where it exhibits a protumor function through a paracrine and/or autocrine mechanism." (PMID 40626360, 2025). "In cancer pathogenesis, GPNMB mediates immune evasion via MDSC recruitment and MHC-I downregulation." (PMID 41180454, 2025). "In cancer, GPNMB is associated with induced epithelial-mesenchymal transition (EMT) and the acquisition of cancer stem cell (CSC) characteristics." (PMID 40625923, 2025). "We also validated the LC substrate candidates CLMP, ICAM1, PCDH17, as well as the cancer-related GPNMB and TIMD4 as substrates." (PMID 40593564, 2025). "Given the important connection between glycolysis and stemness in cancer cells, we next explored the potential role of GPNMB in regulating GSC self-renewal." (PMID 40626360, 2025). "Studies using three-dimensional spheroid cultures have shown that GPNMB is expressed on the surface of dormant cancer cells, enhancing their stem cell-like properties." (PMID 40625923, 2025). "Research has confirmed that GPNMB plays an important role in the expansion of cancer stem cells, prolonging cell survival, and promoting the metastatic phenotype in vivo." (PMID 41180454, 2025). "For instance, a study has shown that the macrophage-derived soluble glycoprotein NMB (GPNMB) induces cancer stemness and metastasis via CD44 and IL-33." (PMID 41174767, 2025). "GPNMB’s immunoregulatory functions are hijacked in disease states, particularly cancer and autoimmunity." (PMID 41180454, 2025).